TIGAR (TP53 induced glycolysis regulatory phosphatase)
Diseases named in the same sentence as TIGAR in open-access papers (continued):
Sharing a sentence is not in itself a finding about the gene and the disease.
leukemia (continued). "In contrast, TIGAR knockdown also promoted the glycolysis in leukemia cells." (PMID 27884166, 2016). "Knockdown of TIGAR led a significant increase of cell apoptosis in human leukemia cells." (PMID 27884166, 2016). "Furthermore, TIGAR knockdown in combination with glycolysis inhibitor 2-DG led leukemia cells to apoptosis." (PMID 27884166, 2016). "Because TIGAR knockdown activated the glycolysis in leukemia cells, we also tested whether the glycolysis inhibitor may show a combinational effect with TIGAR knockdown." (PMID 27884166, 2016). "On the other hand, our results also showed that TIGAR protected leukemia cells from cell death." (PMID 27884166, 2016). "On the one hand, TIGAR inhibited glycolysis through PFKFB3 in leukemia cells." (PMID 27884166, 2016). "In addition, TIGAR knockdown in combined with 2-DG also mildly enhanced cell death/necrosis of leukemia cells." (PMID 27884166, 2016). "Knockdown of TIGAR inhibited the proliferation of human leukemia cells and sensitized leukemia cells to glycolysis inhibitor 2-deoxy-d-glucose (2-DG) both in vitro and in vivo, which may be due to increased apoptosis rate of leukemia cells." (PMID 27884166, 2016). "The potential mechanisms of TIGAR regulating the glycolysis were also tested in leukemia cells." (PMID 27884166, 2016). "In vivo and in vitro, we tested whether glycolysis may induce TIGAR expression and evaluated the combination effect of glycolysis inhibitor and TIGAR knockdown on human leukemia cell proliferation." (PMID 27884166, 2016). "Therefore, high expression of TIGAR inhibited the glycolysis of leukemia cells and led leukemia cells to sensitive to chemotherapy." (PMID 27884166, 2016). "In vivo study confirmed that the knockdown of TIGAR leads to the inhibition of the proliferation of cancer cells and increases the sensitivity of these cells to the anti-glycolytic agent 2-deoxy-D-glycose, therefore increasing the apoptosis of leukemia cells in the xenograft mouse model." (PMID 40277923, 2025). "However, crosstalk between these genes must exist in cancer cells since it has been observed that when TIGAR is eliminated in leukemia cells expressing high levels of TIGAR, PFKFB3 expression increase, and when TIGAR is overexpressed in cells with low levels of TIGAR, PFKFB3 expression decrease." (PMID 30234009, 2018). "TIGAR might have a dual effect on the proliferation of leukemia cell." (PMID 27884166, 2016). "Furthermore, high expression of TIGAR showed an anti-apoptotic effect on human leukemia cells, which may contribute to the poor OS and higher cumulative incidence of relapse in patients with CN-AML treated with chemotherapy." (PMID 27884166, 2016). "In addition, TIGAR knockdown in combination with 2-DG led leukemia cells to apoptosis." (PMID 27884166, 2016). "Next, we investigated whether TIGAR regulated the glycolysis in leukemia cells." (PMID 27884166, 2016). "As most malignant cells were highly glycolytic and produced high levels of ROS and showed low levels of GSH, we first tested the effect of TIGAR knockdown on ROS and GSH in leukemia cells." (PMID 27884166, 2016). "Therefore, we determined to test whether TIGAR affected the expression of PFKFB in leukemia cells." (PMID 27884166, 2016). "The mechanism of TIGAR regulating the cell apoptosis or necrosis and glycolysis of leukemia cells was still not clear." (PMID 27884166, 2016).
leukemia (continued). "In contrast, the glycolytic inhibitor 2-DG did not affect the expression of TIGAR in leukemia cells." (PMID 27884166, 2016). "CoCl2, inducting cell glycolysis, did not enhance the cell apoptosis in leukemia cells with or without TIGAR knockdown." (PMID 27884166, 2016). "As we showed that glycolysis inhibitor 2-DG did not affect the expression of TIGAR, it suggested that 2-DG and TIGAR may affect the leukemia glycolysis through different mechanisms." (PMID 27884166, 2016).
nasopharyngeal carcinoma (7 papers, 2015 to 2024). A carcinoma arising from the nasopharyngeal epithelium. "Further, in nasopharyngeal carcinoma and non-small cell lung cancer, TIGAR has been linked with enhanced invasion and metastasis." (PMID 30823646, 2019). "There is growing evidence that high TIGAR expression is closely associated with adverse clinical outcomes of patients with multiple types of cancer including chronic lymphocytic leukemia, invasive breast cancer, stage II and stage III colorectal cancer and nasopharyngeal carcinoma." (PMID 29753331, 2018). "Our previous study identified a novel nucleoside analog that inhibited cellular growth and induced apoptosis in nasopharyngeal carcinoma (NPC) cell lines via downregulation of TIGAR expression." (PMID 25621025, 2015). "It has also been reported that c-MET inhibition may result in marked downregulation of TIGAR and intracellular production of NADPH in nasopharyngeal cancer." (PMID 32206103, 2020).
pancreatic ductal adenocarcinoma (7 papers, 2019 to 2025). An infiltrating adenocarcinoma that arises from the epithelial cells of the pancreas. "The expression of the TIGAR gene is dynamically regulated during the advancement of pancreatic ductal adenocarcinoma; decreased levels of ROS promote tumor initiation in the premalignant condition, and increased levels of ROS can enable metastatic progression." (PMID 40277923, 2025). "In mouse models, TIGAR can support the development of intestinal and lymphoid tumors and in a model of pancreatic ductal adenocarcinoma (PDAC), loss of TIGAR limited the development of pancreatic premalignancies." (PMID 39636862, 2024). "Recently, it has been shown that TIGAR expression is dynamically regulated during the development of pancreatic ductal adenocarcinoma, and that together with NRF2 it has a key role in balancing ROS levels during the carcinogenic process." (PMID 35163828, 2022). "A recent report showed that ROS restriction by TIGAR supports premalignant tumor initiation while restricting metastasis in pancreatic ductal adenocarcinoma, indicating that the complexity of ROS regulation underpins full malignant progression." (PMID 33299528, 2020). "show that TIGAR expression is dynamically regulated during the development of pancreatic ductal adenocarcinoma, resulting in lower levels of ROS to promote tumor initiation in the premalignant condition and higher levels of ROS that enable metastatic progression." (PMID 31983610, 2020). "Using mutant KRAS-driven pancreatic ductal adenocarcinoma (PDAC) mouse models, we show that loss of TIGAR delays the emergence of premalignant pancreatic intraepithelial neoplasia (PanIN) lesions, but enhances the metastatic capacity of the tumor cells, leading to decreased survival." (PMID 31983610, 2020). "Using a pancreatic ductal adenocarcinoma (PDAC) model, researchers found that ROS regulation by TIGAR supports premalignant tumor initiation while restricting metastasis." (PMID 40277923, 2025). "Recently, it has been observed that TIGAR and NRF2 can fulfil similar functions in the initiation and dissemination of mouse pancreatic ductal adenocarcinoma." (PMID 35163828, 2022). "Using a pancreatic ductal adenocarcinoma (PDAC) model, we show that reactive oxygen species (ROS) regulation by TIGAR supports premalignant tumor initiation while restricting metastasis." (PMID 31983610, 2020).
acute myeloid leukemia (6 papers, 2016 to 2025). Acute myeloid leukemia (AML) is a group of neoplasms arising from precursor cells committed to the myeloid cell-line differentiation. "In chronic lymphocytic leukemia, in cytogenetically normal acute myeloid leukemia, and in lung adenocarcinoma, high TIGAR expression and TIGAR protein, were associated with shorter survival." (PMID 30823646, 2019). "TIGAR overexpression is associated with decreased survival of patients with acute myeloid leukemia (AML) and other tumors." (PMID 30234009, 2018). "The function of TIGAR in glycolysis and survival of acute myeloid leukemia cells was studied in vitro and in vivo." (PMID 40277923, 2025). "It was found that the high expression of TIGAR in patients with acute myeloid leukemia can be a predictor of poor survival and a high incidence of relapse." (PMID 40277923, 2025). "In this study, we showed that the expression of TIGAR in patients with cytogenetically normal acute myeloid leukemia (CN-AML) correlated with the clinical features and outcomes." (PMID 27884166, 2016). "However, the function of TIGAR in glycolysis and survival of acute myeloid leukemia cells remains unclear." (PMID 27884166, 2016).
Cerebral ischemia (6 papers, 2016 to 2025). Restriction of arterial blood supply to the brain associated with insufficient oxygenation to support the metabolic requirements of the tissue. "TRIM31 deficiency alleviated mitochondrial injury induced by cerebral ischemia by upregulating the level of TIGAR protein." (PMID 36437984, 2022). "TRIM31 deficiency alleviates mitochondrial damage induced by cerebral ischemia by upregulating TIGAR protein level." (PMID 36437984, 2022). "Mechanistically, TIGAR partially inhibits autophagy by decreasing ROS and activating the mTOR-S6K pathway, thereby preventing cerebral ischemia-induced neuronal injury." (PMID 37856037, 2024). "In 2015, the protective effect of TIGAR on cerebral ischemia–reperfusion injury and brain preconditioning was first reported." (PMID 36437984, 2022). "ISO also increased TIGAR in mouse cortex and hippocampus and alleviated subsequent brain ischemia-reperfusion injury, while the ischemic tolerance induced by ISO was eliminated with TIGAR knockdown in mouse brain." (PMID 27256465, 2016). "In the context of cerebral ischemia, TIGAR has been shown to exert neuroprotective effects by reducing oxidative stress, supporting mitochondrial function, and mediating downregulation of pro-inflammatory markers such as iNOS, COX-2, IL-1β, and TNF-α in astrocytes." (PMID 41342963, 2025). "TIGAR shows neuroprotection in monkey and rodent models of cerebral ischemia." (PMID 37856037, 2024). "These indicate that TIGAR has PPP-independent antioxidant activity in prolonged cerebral ischemia." (PMID 36437984, 2022). "Interestingly, TIGAR’s neuroprotection in long-term cerebral ischemia by alleviating oxidative stress was independent of the pentose phosphate pathway triggered by its phosphatase activity." (PMID 37856037, 2024).
cervical carcinoma (6 papers, 2015 to 2025). A carcinoma arising from either the exocervical squamous epithelium or the endocervical glandular epithelium. "They checked the expression levels of TIGAR protein by screening HPV16+ cervical cancer clinical isolates by confocal microscopy." (PMID 40277923, 2025). "This is in accordance with previous results from our group which showed that in the cervical carcinoma cell line, HeLa inhibition of Akt prevented the induction of TIGAR." (PMID 34299056, 2021). "The overexpression of TIGAR was also shown to serve as a prognostic indicator of advanced tumor growth and invasiveness in cervical cancer patients." (PMID 35291688, 2021). "In HeLa cervical carcinoma cells, TIGAR can be induced in an Akt-dependent manner in response to the inhibition of glycolysis." (PMID 30234009, 2018). "We show here that NRF2 activation increases the expression of TIGAR in the cervical cancer HeLa cell line both in response to NRF2 overexpression and following exposure to the electrophilic molecules SFN and DMF, which induce the dissociation of NRF2 from KEAP1." (PMID 35163828, 2022). "We next tested whether siRNA-knockdown of TIGAR expression could hypersensitize HPV18+ HeLa cervical carcinoma cells to otherwise sub-inhibitory concentrations of the chemotherapeutic agents: doxorubicin, cisplatin, etoposide, or 4-hydroxycyclophosphamide." (PMID 35291688, 2021). "We therefore investigated whether the TIGAR protein is overexpressed in HPV16+ cervical cancer clinical isolates by immunofluorescence-confocal microscopy." (PMID 35291688, 2021). "The results from these studies revealed that the antioxidant effector TIGAR is highly expressed in HPV16+ cervical cancer clinical isolates and could prominently contribute to viral carcinogenesis by protecting rapidly proliferating tumor cells from oxidative stress and ROS-induced apoptosis." (PMID 35291688, 2021). "Thus, to determine if inhibiting TIGAR could sensitize hrHPV+ cervical carcinoma cells to reduced concentrations of etoposide, HeLa cells were cultured on glass coverslips and then transfected with 25 ng of either siRNA-TIGAR or a scrRNA oligonucleotide as a negative control." (PMID 35291688, 2021).
esophageal squamous cell carcinoma (6 papers, 2020 to 2025). Esophageal squamous cell carcinoma (ESCC) is a type of esophageal carcinoma (EC) that can affect any part of the esophagus, but is usually located in the upper or middle third. "Through the targeting of TIGAR, miR-144 was also shown to suppress esophageal squamous cell carcinoma (ESCC) cell proliferation." (PMID 33046994, 2020).
gastric cancer (6 papers, 2019 to 2025). A primary or metastatic malignant neoplasm involving the stomach. "In gastric cancer, TIGAR has been shown to inhibit glycolysis and promote antioxidant activities, leading to increased NADPH production, reduced reactive oxygen species (ROS) levels, and enhanced cancer cell survival." (PMID 40277923, 2025). "Currently, the specific mechanism of the TIGAR is poorly studied, and its relationship with gastric cancer also needs further study." (PMID 35574353, 2022). "We also carried out Kaplan-Meier survival analysis and log-rank test to assess the significance of TIGAR expression in the survival of gastric cancer patients." (PMID 31799200, 2019). "IHC results demonstrated that the expression of TIGAR in gastric cancer tissues was significantly higher than that in adjacent non-cancerous tissues (p < 0.01)." (PMID 31799200, 2019). "In the present study, we found that TIGAR was highly expressed in primary gastric cancers, which is consistent with previous findings of TIGAR expressions in several types of human cancers." (PMID 31799200, 2019). "To assess the significance of TIGAR expression in gastric cancer, we carried out immunohistochemistry analysis using a gastric cancer tissue array." (PMID 31799200, 2019). "Depletion of TIGAR leads to ROS elevation, which likely serves as a main contributor to induced apoptosis in gastric cancer cell." (PMID 31799200, 2019). "Although the effects of TIGAR have been reported previously in other type of cancer, but still remained unexplored in gastric cancer." (PMID 31799200, 2019). "Finally, five proteins, including NDRG1_pT346, SYK, P90RSK, TIGAR, and XBP1, were related to the risk prognosis of gastric cancer and were selected for model construction." (PMID 36979962, 2023). "TIGAR also increased the production of NADPH in gastric cancer cells." (PMID 31799200, 2019). "Therefore, it is important to examine the exact roles of TIGAR in gastric cancer to confirm its oncogenic implications, especially from the clinical perspective." (PMID 31799200, 2019). "Currently, few studies focus on the function of the TIGAR in gastric cancer; thus, future studies need to confirm the relationship of TIGAR with GC prognoses." (PMID 36979962, 2023). "TIGAR expression levels were detected by immunoblotting and immunohistochemistry in gastric cancer samples, along with four established cell lines of GC." (PMID 31799200, 2019). "However, the functions of TIGAR in gastric cancer (GC) remain unclear." (PMID 31799200, 2019).
non-small cell lung carcinoma (6 papers, 2013 to 2022). A group of at least three distinct histological types of lung cancer, including non-small cell squamous cell carcinoma, adenocarcinoma, and large cell carcinoma. "A549 non-small cell lung cancer cells were more sensitive to etoposide, 5-fluorouracil, and cis-dichlorodiamineplatinum when transfected with siRNA-targeting TIGAR." (PMID 30823646, 2019). "Recently, the cytotoxic effects of the DNA methyltransferase inhibitor decitabine and the inhibitor of heme-oxygenase tin mesoporphyrin have been linked to decreased expression of TIGAR and reduced PPP in myeloid leukemia and non-small cell lung carcinoma (NSCLC), respectively." (PMID 35163828, 2022).